RPL38 (ribosomal protein L38)
Description:
Component of the large ribosomal subunit. The ribosome is a large ribonucleoprotein complex responsible for the synthesis of proteins in the cell.
Synonyms: L38; eL38
Tractability: Small molecule: an approved drug acts on it; a structure with a bound ligand is known; a high-quality ligand is known. PROTAC: UniProt records ubiquitination sites on it; ubiquitination databases record sites on it; its protein half-life has been measured; a small molecule that binds it is known. Other modalities: a drug acting on it is in phase 2 or 3 trials.
Target class: Other cytosolic protein
Gene: Protein-coding gene on chromosome 17 (74,202,841 to 74,210,655, forward strand). Ensembl gene ENSG00000172809.
Subcellular location: Cytoplasm
Subcellular location (Human Protein Atlas): Cytosol; Endoplasmic reticulum
Pathways (Reactome):
Metabolism of proteins: Eukaryotic Translation Termination; Formation of a pool of free 40S subunits; GTP hydrolysis and joining of the 60S ribosomal subunit; L13a-mediated translational silencing of Ceruloplasmin expression; PELO:HBS1L and ABCE1 dissociate a ribosome on a non-stop mRNA; Peptide chain elongation; Ribosome Quality Control (RQC) complex extracts and degrades nascent peptide; SRP-dependent cotranslational protein targeting to membrane; ZNF598 and the Ribosome-associated Quality Trigger (RQT) complex dissociate a ribosome stalled on a no-go mRNA
Metabolism of RNA: Major pathway of rRNA processing in the nucleolus and cytosol; Nonsense Mediated Decay (NMD) enhanced by the Exon Junction Complex (EJC); Nonsense Mediated Decay (NMD) independent of the Exon Junction Complex (EJC)
Cellular responses to stimuli: Response of EIF2AK4 (GCN2) to amino acid deficiency
Developmental Biology: Regulation of expression of SLITs and ROBOs
Disease: Viral mRNA Translation
Metabolism: Selenocysteine synthesis
Gene Ontology:
Molecular function: protein binding; structural constituent of ribosome; RNA binding
Biological process: cytoplasmic translation; negative regulation of myoblast fusion; spermatogenesis; striated muscle contraction; translation
Cellular component: cytoplasm; cytosol; cytosolic large ribosomal subunit; cytosolic ribosome; endoplasmic reticulum; focal adhesion; postsynaptic density; eukaryotic 80S initiation complex; ribosome; synapse
Genetic constraint (gnomAD): Loss-of-function variants: 2 observed, 13.66 expected, observed/expected ratio (o/e) 0.15, 90% interval 0.059 to 0.46. The upper end of that interval is the gene's LOEUF score, 0.46, which puts it in group 2 of 6, group 1 being the genes least tolerant of losing a copy. Missense variants: 52 observed, 81.38 expected, observed/expected ratio (o/e) 0.64, 90% interval 0.51 to 0.81. Synonymous variants: 40 observed, 31.1 expected, observed/expected ratio (o/e) 1.29, 90% interval 1 to 1.67.
Homologues: Orthologues: chimpanzee RPL38 (100% identical), guinea pig RPL38 (100% identical), macaque RPL38 (100% identical), pig RPL38 (100% identical), zebrafish rpl38 (100% identical), mouse Rpl38 (99% identical), rabbit RPL38 (99% identical), tropical clawed frog rpl38 (87% identical), Caenorhabditis elegans rpl-38 (79% identical), Drosophila melanogaster RpL38 (73% identical).
Diseases named in the same sentence as RPL38 in open-access papers:
RPL38 is named in the same sentence as 25 diseases in open-access papers, as found by Europe PMC text mining. Sharing a sentence is not in itself a finding about the gene and the disease. The quoted sentences say what the papers report.
lymphoma (4 papers, 2015 to 2023). A malignant (clonal) proliferation of B- lymphocytes or T- lymphocytes which involves the lymph nodes, bone marrow and/or extranodal sites. "Haplo-insufficiency of the ribosomal proteins eL24 (RPL24) or eL38 (RPL38) has been shown to prevent lymphoma induction in a transgenic EμMyc mouse model." (PMID 36140189, 2022). "Moreover, the mandatory role of the ribosome in Myc-dependent transformation was elegantly demonstrated as haploinsufficiency of the eL24 (RPL24) or eL38 (RPL38) ribosomal proteins prevented lymphoma induction in a transgenic in EμMyc mouse model." (PMID 32151059, 2020).
breast carcinoma (3 papers, 2017 to 2023). "Together, combining our systems biology analysis with a dual validation approach, we have confirmed/validated only two intrinsic biomarkers, RPL13 and RPL38, for Luminal-A breast cancers." (PMID 35971177, 2022). "Surprisingly, in our omics data, we also observed down-regulation for RPL13 expression (PRG treatment only) and RPL38 expression (PRG treatment and CSC-KD) in nPR(+) T47D cells (panel A1), validating their role as intrinsic biomarkers in Luminal-A breast cancers." (PMID 35971177, 2022).
anemia (1 paper, 2016). A reduction in the number of red blood cells, the amount of hemoglobin, and/or the volume of packed red blood cells. "We also compare expression of rpl38, which has not yet been identified in human disease but heterozygous loss in mice results in anemia and skeletal malformations." (PMID 27784267, 2016).
asplenia (1 paper, 2020). "Prominent examples are RPS14/uS11, RPSA/uS2 and RPL38/eL38 genes with mutations associated with 5q- myelodysplastic syndrome, isolated congenital asplenia and skeletal defects during embryogenesis, including perturbations in the formation of the axial skeleton." (PMID 33575632, 2020).
Brain atrophy (1 paper, 2022). Partial or complete wasting (loss) of brain tissue that was once present. "For example, mutations in Rplp1 result in brain atrophy, male infertility, and kinked tails whereas the Rpl38 mutant mice exhibit craniofacial dysmorphia, microphthalmia, exencephaly, and homeotic transformations of the axial skeleton." (PMID 35013307, 2022).
colorectal cancer (1 paper, 2023). A primary or metastatic malignant neoplasm that affects the colon or rectum. "Because FIRΔexon2 is detected in colorectal cancer tissues, the expressions of RPL30, RPL37A, RPL38, RPS14, and RPS29 mRNAs by the effect of FIRΔexon2 were examined in HCT116 cells." (PMID 38139171, 2023).
endometriosis (1 paper, 2016). The growth of functional endometrial tissue in anatomic sites outside the uterine body. "Among the selected genes, SNORD116, RPLP2, RPL38 and 40S ribosomal protein S28 (RPS28) were most elevated ones in endometriosis patients, which was consistent with our in vitro experimental findings using miR196a2-C vector." (PMID 27741504, 2016).
gastric cancer (1 paper, 2022). A primary or metastatic malignant neoplasm involving the stomach. "Ribosomal protein L38 (RPL38) controls proliferation and apoptosis in gastric cancer through the miR-374b-5p/vascular endothelial growth factor (VEGF) signaling pathway and is overexpressed in a resistant BC ductal cell line." (PMID 36072666, 2022).
Granuloma (1 paper, 2017). A compact, organized collection of mature mononuclear phagocytes, which may be but is not necessarily accompanied by accessory features such as necrosis. "Cholesterol granulomas are seen in mice with a semi-dominant point mutation in the gene encoding ribosomal protein L38 (Rpl38) and in mice with a semi-dominant mutation in the gene encoding the nuclear scaffold lamin A/C proteins (Lmna)." (PMID 29125825, 2017).
squamous cell carcinoma (1 paper, 2023). A carcinoma arising from squamous epithelial cells. "Genes involved in alternative splicing in squamous cell carcinoma are rich in RPs and splicing factors, including ribosomal protein L38 (RPL38)." (PMID 38002277, 2023).
X-linked dyskeratosis congenita (1 paper, 2015). "The idea that perturbations in ribosome structure may deregulate translation of mRNAs encoding cancer-promoting proteins is supported by published data, as illustrated by X-linked dyskeratosis congenita or from research performed on single mutated genes coding for RPs, as RPL38 or RPL10." (PMID 25886394, 2015).
tumor (7 papers, 2013 to 2026). "Lastly, we validated the expression of the five RBRS genes (RPL38, RPS2, RPS14, RPS19, and RPS28) using qRT-PCR on tumor and adjacent normal samples from 12 ccRCC patients at Meizhou Hospital." (PMID 40642093, 2025).
cancer (5 papers, 2018 to 2026). A tumor composed of atypical neoplastic, often pleomorphic cells that invade other tissues. "Multi-omics analyses-including pan-cancer cohorts and spatial transcriptomics-were integrated to evaluate the expression and prognostic significance of Ribosomal Protein L38 (RPL38)." (PMID 41766901, 2026). "Additionally, RPL38 has been identified as a cancer immunotherapy protein and a potential target for immunotherapy in BC." (PMID 37922300, 2023). "Indeed, we observed increased proliferation of human NSPCs in adherent monolayer cultures and in brain organoids after experimentally increasing the levels of a single ribosomal protein, RPL38, that has been previously associated with HOX gene regulation and cell division in cancer cells." (PMID 34525348, 2021). "Best predicted cancer immunotherapy proteins with BC were RPS27, SUPT4H1, CLPSL2, POLR2K and RPL38, and the most altered ones were POLR2K, ASH2L, MED30, NSL1 and RPRD2." (PMID 32444848, 2020).
RPL38 also shares sentences with these, for which no sentence is quoted: B-cell lymphoma (1 paper); developmental delay (1); infection (1); lung adenocarcinoma (1); male infertility (1); microphthalmia (1); myelodysplastic syndrome (1); paraganglioma (1); pheochromocytoma (1); prostate carcinoma (1); thymoma (1); thyroid cancer (1).